GJB7 (gap junction protein beta 7)
Description:
One gap junction consists of a cluster of closely packed pairs of transmembrane channels, the connexons, through which materials of low MW diffuse from one cell to a neighboring cell.
Synonyms: Cx25; bA136M9.1; connexin25
Tractability: Antibody: UniProt places it where antibodies can reach, with medium confidence; UniProt predicts a signal peptide or a membrane-spanning region; its Gene Ontology location is reachable by antibodies, with medium confidence; the Human Protein Atlas places it where antibodies can reach.
Gene: Protein-coding gene on chromosome 6 (87,282,980 to 87,329,278, reverse strand). Ensembl gene ENSG00000164411.
Subcellular location: Cell membrane; Cell junction, gap junction
Subcellular location (Human Protein Atlas): Cytosol; Plasma membrane
Pathways (Reactome):
Vesicle-mediated transport: Gap junction assembly
Gene Ontology:
Molecular function: gap junction channel activity
Biological process: transmembrane transport; cell-cell signaling; cell communication
Cellular component: connexin complex; gap junction; plasma membrane
Genetic constraint (gnomAD): Loss-of-function variants: 5 observed, 1.85 expected, observed/expected ratio (o/e) 2.7. That is too few expected variants to judge how well the gene tolerates losing a copy. Missense variants: 253 observed, 270.38 expected, observed/expected ratio (o/e) 0.94, 90% interval 0.84 to 1.04. Synonymous variants: 87 observed, 100.65 expected, observed/expected ratio (o/e) 0.86, 90% interval 0.73 to 1.03.
Homologues: Orthologues: chimpanzee GJB7 (99% identical), pig GJB7 (90% identical), rabbit GJB7 (83% identical), dog GJB7 (82% identical), tropical clawed frog gjb7 (72% identical), zebrafish gjb7 (56% identical). Paralogues in human: GJB3 (57% identical), GJB5 (56% identical), GJB4 (54% identical), GJB2 (48% identical), GJB1 (47% identical), GJA3 (46% identical), GJB6 (46% identical), GJA8 (46% identical), GJA9 (43% identical), GJA1 (43% identical), GJA4 (42% identical), GJA10 (41% identical), and 8 more.
Diseases named in the same sentence as GJB7 in open-access papers:
GJB7 is named in the same sentence as 6 diseases in open-access papers, as found by Europe PMC text mining. Sharing a sentence is not in itself a finding about the gene and the disease. The quoted sentences say what the papers report.
leukemia (2 papers, 2015 to 2020). A malignant (clonal) hematologic disorder, involving hematopoietic stem cells and characterized by the presence of primitive or atypical myeloid or lymphoid cells in the bone marrow and the blood. "Studies have proved that GJB7 was a specific gap junction protein associated with cell communication and disrupted by RNAi could increase chemotherapy sensitivity in leukemia." (PMID 32266149, 2020).
cancer (1 paper, 2020). A tumor composed of atypical neoplastic, often pleomorphic cells that invade other tissues. "We also found the genotype of rs16879870 and rs854936 was significantly associated with the expression of gene GJB7 (P = 0.013) and RTN4R (P = 0.047) in cancer tissues of TCGA, respectively." (PMID 32266149, 2020). "The gene expression of GJB7 and RTN4R in cancer tissues were obviously higher than normal tissues (P = 5.42 × 10−8 and 4.55 × 10−12 for GJB7 and RTN4R, respectively)." (PMID 32266149, 2020).
GJB7 also shares sentences with these, for which no sentence is quoted: acute lymphoblastic leukemia (1 paper); non-Hodgkin lymphoma (1); prostate carcinoma (1); tumor (1).